CTSD (cathepsin D)
Diseases named in the same sentence as CTSD in open-access papers (continued):
Sharing a sentence is not in itself a finding about the gene and the disease.
synucleinopathy (3 papers, 2015 to 2025). A neurodegenerative disease that is characterized by the abnormal accumulation of aggregates of alpha-synuclein protein in neurons, nerve fibers or glial cells. "Recovery of synaptic distribution was also evident in recent studies after treatment of synucleinopathy models with recombinant CTSD (rHsCTSD) as well as GCase activators, both restoring SNCA pathology while normalizing Synapsin-1 expression and localization." (PMID 40883786, 2025). "Moreover, low levels of CTSB have been found in PD CSF samples, indicating that reduced activities of CTSD and CTSB are strongly associated with PD and other synucleinopathies." (PMID 37312133, 2023).
thyroid cancer (3 papers, 2018 to 2023). "INSL3 was also demonstrated to promote early tumor cell invasiveness in human thyroid carcinoma cells by enhancing their metabolic activity and elastin-degrading potential via increasing the production of the lysosomal enzymes cathepsin-L and cathepsin-D." (PMID 34211824, 2021).
asthma (2 papers, 2013 to 2022). "CTSD, H and K were also detected in airway tissues from people with and without asthma." (PMID 23483898, 2013).
bone cancer (2 papers, 2019 to 2023). A primary or metastatic malignant neoplasm affecting the bone or articular cartilage. "Additionally, bone tumor studies acknowledged elevated CTSD expression promotes bone metastasis and bone tumor progression." (PMID 37198626, 2023).
brain tumors (2 papers, 2019 to 2026). "Evidence of a role for cathepsin D in brain tumors, particularly MG, has so far been inconclusive." (PMID 30949483, 2019).
Cerebral ischemia (2 papers, 2020 to 2024). Restriction of arterial blood supply to the brain associated with insufficient oxygenation to support the metabolic requirements of the tissue. "In our present study, the enzymatic activities of CTSB and CTSD were also altered after OGD/R treatment, suggesting that TMEM175 deficiency exerts a negative effect on the hydrolytic function of lysosomes following cerebral ischemia with reperfusion." (PMID 32799888, 2020). "Western blot demonstrated that cerebral ischemia created an autophagic/lysosomal dysfunction, as reflected by increased autophagic substrates of LC3-II, ubiquitinated proteins and insoluble p62, accompanied by decreased lysosomal CTSD." (PMID 39155286, 2024).
chronic kidney disease (2 papers, 2016 to 2017). Impairment of the renal function secondary to chronic kidney damage persisting for three or more months. "In line with this, previous study showed that cathepsin D could be a marker for early diagnosis and target for treatment of cardiovascular diseases in patients with chronic kidney disease." (PMID 29375176, 2017). "Thus, CtsD but not B inhibition lead to a reduction in kidney fibrosis in two different models of chronic kidney disease." (PMID 26831567, 2016).
colon adenocarcinoma (2 papers, 2019 to 2025). "CTSD expression was significantly higher in AML compared to other cancers, including TNBC, colon adenocarcinoma (COAD), and others." (PMID 40796615, 2025).
colorectal tumor (2 papers, 2012 to 2020). "CTSD is highly expressed in colorectal tumors and positively correlated with the expression of EGFR." (PMID 32331211, 2020). "Cathepsin D was found to have different expressions in three different areas of interest of colorectal tumor tissues in our discovery project." (PMID 22919486, 2012). "High-level expression of cathepsin D at the IF area of colorectal tumor did not correlate significantly with any of the clinico-pathological parameters examined (data not shown)." (PMID 22919486, 2012). "The presence of macrophages containing cathepsin D at the IF area of colorectal tumor did not correlate significantly with any of the clinico-pathological parameters examined (data not shown)." (PMID 22919486, 2012).
cystic fibrosis (2 papers, 2015 to 2022). Autosomal recessive disorder caused by pathogenic variants in the CFTR gene (cystic fibrosis transmembrane conductance regulator), which encodes a chloride and bicarbonate channel expressed in epithelial cells, and follow the diagnosis criteria. "CTSD, a protease that breaks down abnormal or denatured proteins in airway, was more expressed with lung inflammation, especially in cystic fibrosis." (PMID 36076228, 2022).
depression (2 papers, 2012 to 2020). "In this regard, heterozygous CTSD-deficient mice exhibit BD characteristics, such as mania-related behavior and stress-induced depression." (PMID 32325768, 2020). "ACTB, CKB, NEFL, INA and GFAP had link to both schizophrenia and depression, while CTSD, HSPA8, NEFM and TUBA1A had link to schizophrenia." (PMID 23272063, 2012).
diabetic retinopathy (2 papers, 2025). "CTSB and CTSD are instrumental in the progression of diabetic retinopathy, highlighting their crucial roles in its worsening condition." (PMID 39964999, 2025). "Previous study has indicated higher CTSD levels in patients with T2DM and severity of diabetic retinopathy." (PMID 41480144, 2025).
dilated cardiomyopathy (2 papers, 2016 to 2021). Cardiomyopathy which is characterized by dilation and contractile dysfunction of the left and right ventricles. "Cathepsin D is an autophagy-related enzyme and it has been found up-regulated in a hamster model of dilated cardiomyopathy." (PMID 27317124, 2016).
endometrial adenocarcinoma (2 papers, 1996 to 1999). "Total cytosolic cathepsin D (Cat D) levels were estimated by an immunoradiometric assay in a series of 156 consecutive patients with surgical stages I–III primary endometrial adenocarcinoma." (PMID 10027332, 1999). "The present study investigates the prognostic value of immunohistochemically detected cathepsin D expression in endometrial adenocarcinoma." (PMID 8664123, 1996). "Immunohistochemical detection of cathepsin D could aid in predicting prognosis and planning therapy for patients with endometrial adenocarcinoma." (PMID 8664123, 1996).
head and neck squamous cell carcinoma (2 papers, 2015 to 2024). A squamous cell carcinoma that arises from any of the following anatomic sites: lip and oral cavity, nasal cavity, paranasal sinuses, pharynx, larynx, and salivary glands. "Several studies have found that cathepsin D gene expression was associated with metastasis in head and neck squamous cell carcinoma." (PMID 38398017, 2024). "While cathepsin D has been studied mostly in the context of breast cancer patients, several authors have examined its role in head and neck squamous cell carcinoma." (PMID 38398017, 2024).
hepatic disease (2 papers, 2021 to 2024). "Regardless of lipid metabolism, in the current study, we also demonstrate an independent association between plasma CTSD levels and hepatic disease markers (LSM, AST/ALT ratio and AST)." (PMID 39263329, 2024). "Moreover, multiple linear regression analyses were performed to further evaluate whether plasma CTSD levels were independently associated with these hepatic disease parameters." (PMID 39263329, 2024). "Subsequently, the accuracy of plasma CTSD levels alone or in combination with known non-invasive markers of hepatic disease was investigated in patients with MetALD/ALD." (PMID 39263329, 2024). "Considering its association with MetALD/ALD, we next examined the liver specificity of plasma CTSD levels by correlating their values with hepatic disease markers." (PMID 39263329, 2024). "Altogether, these results illustrate the value of plasma CTSD levels for MetALD/ALD prediction when combined with two other hepatic disease parameters." (PMID 39263329, 2024). "The addition of plasma CTSD to AST/ALT ratio (AUC = 0.858; p <0.0001) and LSM (AUC = 0.857; p = 0.0258) significantly increased the diagnostic accuracy of both hepatic disease parameters." (PMID 39263329, 2024). "While hepatic disease parameters (AST/ALT ratio, liver stiffness measurement) were higher at advanced histopathological stages (assessed by liver biopsy), plasma CTSD levels were already elevated at early histopathological stages." (PMID 39263329, 2024). "Furthermore, the NAS inflammation score confirmed these findings: while the existing hepatic disease markers AST/ALT ratio and LSM significantly increased at advanced NAS inflammation scores, plasma CTSD levels were highest at the lowest NAS inflammation scores." (PMID 39263329, 2024).
hypertriglyceridemia (2 papers, 2014 to 2016). A laboratory test result indicating elevated triglyceride concentration in the blood. "Biochemical findings include transient cobalamin deficiency, severe hypertriglyceridemia upon ketogenic diet, microalbuminuria and partial cathepsin D deficiency." (PMID 25233840, 2014).
infantile hemangioma (2 papers, 2017 to 2019). "To further characterize the cathepsin D+ (red) and cathepsin G+ (red) cells, we performed co-staining with tryptase, as we have reported in infantile hemangioma." (PMID 28775982, 2017). "However, cathepsin D is localized only to the CSC subpopulation within the TNs, while cathepsin G is localized exclusively to the tryptase+ phenotypic mast cells within the peri-tumoral stroma, similar to the finding in infantile hemangioma." (PMID 28775982, 2017).
injury (2 papers, 2011 to 2024). Damage inflicted on the body as the direct or indirect result of an external force, with or without disruption of structural continuity. "Decreased levels and activity of the lysosomal protein cathepsin D were also recently reported in CNS trauma, such as traumatic brain injury and spinal cord injury, frequently accompanied by inhibition of autophagy flux." (PMID 38812004, 2024). "They showed that, after skin injury, HLP1 is proteolysed by cathepsin D to increase the levels of antimicrobial peptide parasin I. Contrary to effects caused by acute stress, chronic stress decreases the transcriptional levels of HLP1 in catfish before any signs of illness can occur." (PMID 22204309, 2011).
invasive breast carcinoma (2 papers, 1995 to 2024). A carcinoma that infiltrates the breast parenchyma. "We analysed 213 primary invasive breast cancers for cathepsin D expression from archival tissue with immunohistochemistry." (PMID 7819033, 1995).
ischemic stroke (2 papers, 2021 to 2024). A stroke disorder caused by obstruction of blood flow to the brain, due to thrombotic (local blood clot formation) or embolic (due to a blood clot or other material traveling from another site) event. "A recent study also demonstrated that EE promoted autophagy by increasing the expression of beclin-1 and enhancing the lysosomal activities of lysosomal-associated membrane protein 1, cathepsin B, and cathepsin D, which eventually boosted neurological function recovery following ischemic stroke." (PMID 34646128, 2021).
keratoconus (2 papers, 2022 to 2023). A degenerative, structural disorder of the eye, characterized by a cone-shaped protrusion of the cornea. "In corneal stromal cells, we identified two novel keratoconus-related markers, namely cathepsin D (CTSD) and cathepsin K (CTSK)." (PMID 35821117, 2022). "Importantly, the authors identified cathepsin D (CTSD), cathepsin K (CTSK), YES-associated protein 1 (YAP1), and TEA domain transcription factor (TEAD1) as novel biomarkers in keratoconus stromal cells." (PMID 37138096, 2023). "We then evaluated the subtype-specific expression of the keratoconus-related enzymes identified in this study, and found that CTSD was specifically and highly expressed in keratoconus across all subtypes, while CTSK was mainly differentially enriched in C0-C2 cells." (PMID 35821117, 2022). "Consistent with the detected changes in mRNA levels, immunohistochemical analyses confirmed increased CTSD and CTSK protein levels in keratoconus stromal cells." (PMID 35821117, 2022). "Among these genes, two lysosomal cysteine proteases CTSD and CTSK were identified, providing potential biomarkers for keratoconus diagnosis." (PMID 35821117, 2022). "Further cyclical mechanical experiments revealed that several protease genes (including MMP1, MMP3, CTSD and CTSK) can be induced by stretch, indicating the inductive role of mechanical stretch in keratoconus pathogenesis." (PMID 35821117, 2022). "Further cyclical mechanical experiments on human corneal stromal cell lines demonstrated that mechanical stretch prompted the expression of several protease genes, including MMP1, MMP3, CTSD and CTSK, implying the activating effect of mechanical stretch on proteases during keratoconus progression." (PMID 35821117, 2022).
kidney injuries (2 papers, 2018 to 2019). "In the kidney, cathepsin D is enriched in renal proximal tubular epithelial cells, and its levels increase during acute kidney injury." (PMID 30959855, 2019).
lung diseases (2 papers, 2011 to 2013). "In summary, cathepsin D was essential for apoptosis-associated pneumococcal killing and in the absence of cathepsin D expression by macrophages there was evidence of impaired bacterial clearance and markers of more extensive pulmonary disease." (PMID 21298030, 2011). "Cathepsins play a role in ECM remodelling, with cathepsin D, H and K (CTSD, CTSH and CTSK) being associated with lung diseases." (PMID 23483898, 2013).
lymphoma (2 papers, 2014). A malignant (clonal) proliferation of B- lymphocytes or T- lymphocytes which involves the lymph nodes, bone marrow and/or extranodal sites. "It was also recently reported that 2-phenylethynesulfonamide caused the environment of lysosome permeabilization and cathepsin D release from lysosomes in lymphoma cells." (PMID 25159299, 2014). "The expression pattern of cathepsin D and TGM2 suggested that they are not expressed by lymphoma cells, but rather macrophages." (PMID 25362242, 2014).
Lysosomal disease (2 papers, 2012 to 2021). "In addition, we monitored the RNA expression levels of cathepsin‐D, cathepsin‐A, glucocerebrosidase, α‐galactosidase, and mucolipin‐1, previously shown to be upregulated in lysosomal diseases, and found all of them to be upregulated in brains of terminally scrapie‐sick mice." (PMID 34291577, 2021).
microcephaly (2 papers, 2014 to 2022). A congenital or acquired developmental disorder in which the circumference of the head is smaller than normal for the person's age and sex. "For example, primary cathepsin D deficiency, causes early onset epileptic encephalopathy and microcephaly, features, which are prominent in our patient’s clinical phenotype." (PMID 25233840, 2014).
Minimal change disease (2 papers, 2021 to 2023). "Immunohistochemically staining of human kidney biopsy specimens indicated that the expression of cathepsin D was significantly increased in Minimal change disease compared to that in FSGS maybe because of a high level of autophagic activity." (PMID 33633212, 2021).
osteoarthritis (2 papers, 2021 to 2022). A noninflammatory degenerative joint disease occurring chiefly in older persons, characterized by degeneration of the articular cartilage, hypertrophy of bone at the margins and changes in the synovial membrane. "Furthermore, inflammation modulators (such as CSTB, CTSD, and CTSZ), which have been reported to contribute to osteoarthritis, were more highly expressed in the medial than lateral meniscus." (PMID 34360947, 2021).
postmenopausal osteoporosis (2 papers, 2021 to 2022). Metabolic disorder associated with fractures of the femoral neck, vertebrae, and distal forearm. "In conclusion, the integrative bioinformatics analysis and real-time PCR analysis were utilized to offer fresh light into the role of monocytes in premenopausal osteoporosis and identified FOS, PTPN6, and CTSD as potential biomarkers for postmenopausal osteoporosis." (PMID 35095774, 2021).
renal cell carcinoma (2 papers, 2009 to 2023). "Comparative 2D PAGE profiling of CM from renal cell carcinoma (RCC) and normal renal cultures identified cathepsin D that was subsequently validated in urine samples from 239 patients and healthy and benign disease subjects." (PMID 19789534, 2009). "Although there are several potential biomarkers for renal cell carcinoma diagnosis or prognosis, such as Cathepsin D and peptide panel, no validated RCC prognostic biomarker is currently used in clinical patient care." (PMID 37374025, 2023).
restrictive cardiomyopathy (2 papers, 2020 to 2021). A type of heart disorder referring to the inability of the ventricles to fill with blood because the myocardium (heart muscle) stiffens and looses its flexibility. "Although the heart of CTSD-/- mice shows restrictive cardiomyopathy along with myocardial ATPSC and LC3-II deposits, its ejection fraction is maintained." (PMID 32176724, 2020).
sarcopenia (2 papers, 2021 to 2025). Progressive decline in muscle mass due to aging which results in decreased functional capacity of muscles. "This study explores the relationship between circulating cathepsin K (CatK) and cathepsin D (CatD) levels and sarcopenia in older adults." (PMID 41001380, 2025). "An immunoassay study found that the level of cathepsin D in the serum of patients with sarcopenia was higher than in normal people." (PMID 34943268, 2021). "Their MS analysis revealed that the sarcopenia group showed 2-fold higher cathepsin D levels and 4.2-fold higher S100A8 levels than the control group." (PMID 34943268, 2021).
schizophrenia (2 papers, 2012 to 2020). A major psychotic disorder characterized by abnormalities in the perception or expression of reality. "In post mortem brains of patients with schizophrenia, CTSD protein abundance has been observed to be reduced in schizophrenia, compared to healthy controls." (PMID 32793006, 2020).
scrapie (2 papers, 2021 to 2025). A fatal disease of the nervous system in sheep and goats, characterized by pruritus, debility, and locomotor incoordination. "In conclusion, we identified abnormal accumulation of proteolytic stress-related proteins, including CD10, cathepsin B, cathepsin D, and MMP9, in the brains of ME7 scrapie-infected mice and sporadic CJD patients." (PMID 40302732, 2025). "In detail, the expression levels of CD10, cathepsin B, cathepsin D, and MMP9-40 kDa were upregulated in ME7 scrapie-infected mice." (PMID 40302732, 2025). "Similar to the western blotting results in ME7 scrapie-infected mice, the expression levels of CD10, cathepsin B, cathepsin D, and MMP9-40 kDa were upregulated in sporadic CJD patients." (PMID 40302732, 2025). "We observed an abnormal accumulation of proteolytic stress-related proteins, including CD10, cathepsin B, cathepsin D, and matrix metalloproteinase 9 (MMP9), in the brains of ME7 scrapie-infected mice and sporadic CJD patients." (PMID 40302732, 2025). "Notably, proteolytic stress-related proteins, including CD10, cathepsin B, cathepsin D, and MMP9, were also upregulated in the cerebral cortex and caudate putamen of ME7 scrapie-infected mice compared to matched controls." (PMID 40302732, 2025). "Notably, proteolytic stress-related proteins, including CD10, cathepsin B, cathepsin D, and matrix metalloproteinase 9 (MMP9), showed altered expression patterns in ME7 scrapie-infected mice compared to matched controls." (PMID 40302732, 2025).
type 1 diabetes (2 papers, 2020 to 2023). "Singh and colleagues also reported that youths with type 1 diabetes excreted higher amounts of lumican, CD14, and various lysosomal proteins such as ASAH1, CTSD, and NAGA compared to their non-diabetic siblings." (PMID 32453760, 2020).
ureteric obstruction (2 papers, 2016 to 2017). "Additionally, activity of CTSD was increased in kidneys of two independent CKD mouse models (unilateral ureteric obstruction (UUO) and chronic ischemia reperfusion injury (IRI) vs. respective controls) and its inhibition by pepstatin A effectively reduced interstitial fibrosis." (PMID 29123184, 2017).